ZNF805 (zinc finger protein 805)
Description:
May be involved in transcriptional regulation.
Tractability: PROTAC: ubiquitination databases record sites on it.
Gene: Protein-coding gene on chromosome 19 (57,240,632 to 57,262,728, forward strand). Ensembl gene ENSG00000204524.
Subcellular location: Nucleus
Subcellular location (Human Protein Atlas): Nucleoplasm
Gene Ontology:
Molecular function: DNA-binding transcription factor activity, RNA polymerase II-specific; RNA polymerase II cis-regulatory region sequence-specific DNA binding
Biological process: regulation of transcription by RNA polymerase II; regulation of DNA-templated transcription
Cellular component: nucleus
Genetic constraint (gnomAD): Loss-of-function variants: 11 observed, 14.5 expected, observed/expected ratio (o/e) 0.76, 90% interval 0.48 to 1.26. The upper end of that interval is the gene's LOEUF score, 1.26, which puts it in group 5 of 6, group 1 being the genes least tolerant of losing a copy. Missense variants: 599 observed, 742.11 expected, observed/expected ratio (o/e) 0.81, 90% interval 0.75 to 0.86. Synonymous variants: 292 observed, 269.51 expected, observed/expected ratio (o/e) 1.08, 90% interval 0.98 to 1.19.
Homologues: Orthologues: chimpanzee ZNF805 (99% identical), macaque ZNF805 (95% identical), dog ZNF805 (86% identical), Drosophila melanogaster CG3281 (22% identical), Drosophila melanogaster CG2712 (20% identical), Drosophila melanogaster Phs (19% identical). Paralogues in human: ZNF264 (85% identical), ZNF599 (54% identical), ZNF550 (39% identical), ZFP37 (37% identical), ZFP90 (37% identical), ZNF582 (37% identical), ZNF133 (36% identical), ZNF404 (36% identical), ZNF266 (36% identical), ZNF614 (35% identical), ZNF25 (35% identical), ZNF875 (35% identical), and 50 more.